INS (insulin)
Diseases named in the same sentence as INS in open-access papers (continued):
Sharing a sentence is not in itself a finding about the gene and the disease.
type 1 diabetes (continued). "Supplementation of 40 grams of L-alanine and 10 grams of glucose with NPH insulin before bed maintained healthy blood glucose levels more consistently than having a snack with the NPH to patients with type 1 diabetes." (PMID 29441044, 2018). "Some limitations include that only fasting/random C-peptide measurements were available for about 60% of individuals, whereas stimulated C-peptide is more appropriate to evaluate insulin secretion in type 1 diabetes." (PMID 29404672, 2018). "There were specific functions to log or calculate insulin dosages in mobile apps employed in the 4/11 (36.3%) studies with type 1 diabetes participants." (PMID 29929949, 2018). "Currently, islet transplantations allow type 1 diabetes patients to produce insulin independently for approximately 1–2 years, with diminishing success 2–5 years after transplantation." (PMID 30098928, 2018). "In type 1 diabetes (T1D), this manifests as destruction of the insulin-secreting β cells, resulting in a life-long dependency on recombinant insulin." (PMID 29541078, 2018). "On the contrary, type 1 diabetes (T1D) occurs as a result of autoimmune destruction of the insulin‐producing cells of the pancreas." (PMID 29713471, 2018). "Out of 189 Type 1 Diabetes patients who were on basal-bolus insulin therapy with insulin degludec, 30 patients matched the inclusion criteria, 17 were males and 13 were females." (PMID 30069184, 2018). "The effects of basal insulin suspension at the start of exercise on blood glucose levels during continuous versus circuit-based exercise in individuals with type 1 diabetes on continuous subcutaneous insulin infusion." (PMID 29527102, 2018). "Type 1 diabetes (T1D) results from the immune-mediated destruction of insulin-producing pancreatic beta cells leading to insulin deficiency in affected individuals." (PMID 30622969, 2018). "Type 1 diabetes results from the autoimmune destruction of the pancreas’s beta cells, which produce insulin." (PMID 29596402, 2018). "Type 1 diabetes was an autoimmune disease which resulted from the immune-mediated destruction of insulin-producing pancreatic β cells." (PMID 30356751, 2018). "These patients initially were thought to have type 1 diabetes since several presented with ketosis, and all required initial insulin therapy." (PMID 30280274, 2018). "But among the 29 million people living with Type 1 diabetes in the US there are roughly 100,000 emergency room visits related to insulin dosing every year, a growing health problem." (PMID 30234092, 2018). "Metformin has been shown to have an insulin-sensitizing effect on glycemic control in type 1 diabetes." (PMID 29338714, 2018). "Type 1 diabetes (T1D) is a progressive autoimmune disease in which the insulin-producing beta cells in the pancreatic islets are destroyed by auto-reactive T cells." (PMID 30337545, 2018). "Type 1 diabetes (T1D) is an organ-specific autoimmune disease affecting the insulin producing β cells of the pancreas, leading to absolute insulin deficiency." (PMID 29494662, 2018). "Twenty-nine adults with type 1 diabetes who had metformin added to their insulin therapy for 12 months were compared with 29 adults with type 1 diabetes who remained on insulin-alone therapy." (PMID 29338714, 2018). "For women with type 1 diabetes, 23.1% and 22.4% used insulin pump therapy before and during/after PPC respectively, and 7.5% and 10.7% were taking metformin in early pregnancy before and during/after PPC respectively." (PMID 29744539, 2018). "Enhanced insulin secretion by pulses (gram flour) is attributed to lower GI of mixed diets in non-insulin dependent diabetes patients." (PMID 29527102, 2018). "In the case of islet transplantation for the treatment of insulin-dependent diabetes, the primary constraint is a shortage of transplantable pancreatic islet material, while the desired product is the capacity to secrete insulin upon exposure to glucose." (PMID 29971529, 2018).
type 1 diabetes (continued). "Injection of STZ destroys insulin-producing β cells and has long been used for the generation of Type 1 diabetes phenotypes." (PMID 30425651, 2018). "A recent clinical study reported that the glycated hemoglobin levels of oral SGLT1 inhibitors were lower than placebo in patients with type 1 diabetes who were receiving insulin." (PMID 29765322, 2018). "Type 1 diabetes (T1D) results from a coordinated autoimmune attack of insulin producing beta cells in the pancreas by the innate and adaptive immune systems, beta cell death being predominantly T cell-mediated." (PMID 29930554, 2018). "This especially makes RL well suited for type-1 diabetes since the modelling process of the insulin-kinetic dynamics is complex and requires invasive measurements on the patient or must be fit through a large dataset." (PMID 30693047, 2018). "We propose to extend this idea by using well defined electrical signals to modulate insulin sensitivity for type 1 diabetes treatment." (PMID 32232085, 2018). "Type 1 diabetes is a T cell-mediated autoimmune disease that selectively destroys insulin-producing β-cells." (PMID 29867762, 2018). "I have insulin-dependent diabetes and fly to New York...or further [across several time zones] How do I have to adjust my insulin dosage now?" (PMID 29588269, 2018). "Excellent glycaemic control was achieved with sulfonylurea therapy in the patients in our study, without the usual side-effects of hypoglycaemia and weight gain seen when intensive insulin therapy is used in patients with type 1 diabetes." (PMID 29880308, 2018). "The portal was especially recommended to type 1 diabetes patients (78.3%); those on insulin (84.3%) and patients aged< 65 years (72.4%)." (PMID 29929483, 2018). "Insulin-stimulated skeletal muscle glucose uptake as well as insulin action reduces in type 1 diabetics." (PMID 29338714, 2018). "The current treatment for type 1 diabetes is solely dependent on the administration of exogenous insulin." (PMID 30594258, 2018). "A declining first-phase insulin response (FPIR) is characteristic of the disease process leading to clinical type 1 diabetes." (PMID 29300921, 2018). "For patients with type 1 diabetes and cystic fibrosis-related diabetes, continued insulin management will be maintained after transplant albeit with different insulin requirements according to feeding or immunosuppressive regimen." (PMID 29623219, 2018). "Despite normoglycaemia prior to onset of type 1 diabetes, insulin levels were lower at all time points in DRLyp/Lyp rats and failed to increase with age compared with control rats (p = 0.0004)." (PMID 29209740, 2018). "Type 1 diabetes is an autoimmune disease that results in the progressive destruction of insulin-producing pancreatic β-cells inside the islets of Langerhans." (PMID 29740396, 2018). "Type 1 diabetes mellitus (T1DM) is an endocrine disorder that is characterized by autoimmune destruction of insulin-producing β cells." (PMID 30359326, 2018). "Currently, insulin injections and blood glucose control is still the standard therapeutic methods for type 1 diabetes." (PMID 30013600, 2018). "In people with type 1 diabetes, the time until 50% of the insulin has been absorbed (T50%) occurs twice as fast after intramuscular compared to SC injections into the thigh, and this difference is even more evident during light physical activity." (PMID 30116732, 2018). "Previous studies have disclosed that HEASCs from eyelid adipose tissue can differentiate into insulin-secreting cells and normalize type I diabetes mice." (PMID 29755530, 2018). "Type 1 diabetes is characterised as an autoimmune disease in which autoreactive T cells infiltrate the pancreatic islets and destroy the insulin producing beta cells." (PMID 29671030, 2018). "Type 1 diabetes (T1D) is an autoimmune disease, in which the insulin-producing Beta cells in the pancreas are destroyed by the immune system, typically leading to complete insulin deficiency." (PMID 29320541, 2018).
type 1 diabetes (continued). "The present analysis reports the incidence and diurnal distribution of hypoglycaemia in adults with type 1 diabetes during home use of hybrid closed‐loop insulin delivery and sensor‐augmented or conventional insulin pump therapy." (PMID 29577536, 2018). "Treatment guidelines for type 1 diabetes, therefore, incorporate early intensive strategies to minimise hypoglycaemia, including multiple daily insulin injections, carbohydrate counting and insulin pumps." (PMID 28983693, 2018). "Studies of adolescents, pediatrics, adults, and overweight adults with type 1 diabetes have been shown the addition of metformin to insulin therapy to reduce insulin dose requirement." (PMID 29338714, 2018). "The artificial pancreas (AP) system is designed to regulate blood glucose in subjects with type 1 diabetes using a continuous glucose monitor informed controller that adjusts insulin infusion via an insulin pump." (PMID 29547553, 2018). "It should also be remembered that a significant proportion of individuals with type 1 diabetes are also obese and that weight gain is a frequent consequence of intensive insulin treatment." (PMID 28501906, 2018). "This meta-analysis was performed to evaluate the efficacy and safety of continuous subcutaneous insulin infusion (CSII) vs. multiple daily injections (MDI) in children with type 1 diabetes." (PMID 30015622, 2018). "Type 1 diabetes, known as insulin‐dependent diabetes, is a chronic condition that results from the autoimmune destruction of beta cells of the pancreas that produce insulin, a hormone needed to allow sugar (glucose) to enter the cells to produce energy." (PMID 30510749, 2018). "More specifically, we will review the use of continuous glucose monitoring (CGM) technologies, the insulin pump and sensor-integrated insulin delivery in care of women with type 1 diabetes in pregnancy." (PMID 29383544, 2018). "T1DM also known as insulin-dependent diabetes, is a chronic condition in which the body produces insufficient insulin." (PMID 29765322, 2018). "We previously reported a boy who was misdiagnosed as type 1 diabetes and was treated with insulin for half a year until he was identified to be GCK-MODY." (PMID 29510678, 2018). "We know from women with type 1 diabetes that the insulin resistant effect of pregnancy declines rapidly, within minutes of the placenta being delivered." (PMID 30089149, 2018). "In adult patients, elevated serum APN levels in type 1 diabetes positively correlate with insulin sensitivity and plasma total antioxidant status." (PMID 29180355, 2018). "A next-generation cure for type 1 diabetes relies on immunoprotection of insulin-producing cells, which can be achieved by their encapsulation in microspheres made of non-covalently crosslinked hydrogels." (PMID 29374272, 2018). "Over 120,000 Australians are currently living with type 1 diabetes and are dependent on injected insulin titrated to food, exercise, stress, and illness." (PMID 29530081, 2018). "Type 1 diabetes (T1D) is an autoimmune disease characterized by the specific destruction of pancreatic insulin-producing β-cells." (PMID 30355671, 2018). "Together, our study demonstrates that Y1 receptor signaling negatively regulates insulin release, and pharmacological inhibition of Y1 receptor signalling for the treatment of non-insulin dependent diabetes should be taken into careful consideration." (PMID 30177746, 2018). "Type 1 diabetes is a complex autoimmune disease characterized by the progressive destruction of the insulin-producing β-cells in the pancreas by autoreactive T lymphocytes." (PMID 30061883, 2018). "In particular, the insulin absence in type-I diabetes results in decreased lipoprotein lipase activity, which, in turn, leads to high levels of VLDL (very low density lipoprotein) and a remarkable HDL (high-density lipoprotein) increase." (PMID 30223606, 2018).
type 1 diabetes (continued). "Type 1 diabetes (T1D) is a progressive autoimmune disease in which the insulin-producing beta cells are destroyed by auto-reactive T cells." (PMID 30337545, 2018). "The next step was to automate the process of insulin replacement in type 1 diabetes – from BG monitoring to insulin delivery controlled by a mathematical algorithm." (PMID 32232090, 2018). "In a cross-sectional study, we evaluated the predictors of lipohypertrophy in 372 type 1 diabetes patients (mean age 17.1 years) receiving subcutaneous insulin with pen and/or syringes for ≥3 months." (PMID 30425682, 2018). "Destruction of insulin-producing β-cells by autoreactive T lymphocytes leads to the development of type 1 diabetes." (PMID 30061883, 2018). "We studied patients with type 1 diabetes because the Atlanta VAMC Endocrinology Telehealth Clinic was created to increase access to specialty care for type 1 diabetes patients who manage their condition with insulin pump therapy." (PMID 29369757, 2018). "Type 1 diabetes (T1D) is an autoimmune condition where insulin-secreting β cells in the islets of Langerhans are destroyed through coordinated attack by both the innate and adaptive immune systems; the final assault being perpetuated by CD8+ cytotoxic T cells." (PMID 29930554, 2018). "The first trial of sensor-integrated insulin delivery in pregnancy included 16 women with type 1 diabetes [37••]." (PMID 29383544, 2018). "In light of this, the traditional treatment for type I diabetes is to restore the blood insulin level by the periodical injection of insulin or the surgical transplantation of functional islets." (PMID 29713373, 2018). "Since 1999, most innovative treatment approaches for treatment of insulin-dependent diabetes have focused on protect beta cell of pancreatic langerhanc islet against auto immunity or replace these cells with insulin producing cells since 1999." (PMID 29373983, 2018). "Previous study demonstrated that the additional insulin administration after ingestion of high fat meal showed an improvement in postprandial TG disposal in type I diabetes." (PMID 29382142, 2018). "Of these people, 437,688 had two type 1 diabetes diagnoses recorded and at least one prescription filled for insulin." (PMID 29115947, 2017). "In contrast, our free-living study enables a more accurate depiction of life with type 1 diabetes, with correction doses of insulin administered pre-meal, thereby providing an unbiased assessment of post-meal glucose excursions." (PMID 28338063, 2017). "Of the 133 subjects with type 1 diabetes, 47 (35.3%) were using an insulin pump and the rest were on multiple daily injections (MDI)." (PMID 28913365, 2017). "The most common treatment for type 1 diabetes with usually little residual insulin secretion is the subcutaneous injection of recombinant human insulin before or after food intake." (PMID 28366620, 2017). "In a very early study performed on type 1 diabetes patients, improvement in metabolic control by insulin therapy significantly lowered Lp(a) level." (PMID 28510610, 2017). "Use of day-and-night hybrid closed-loop insulin delivery under unsupervised, free-living conditions for 4 weeks in adults with type 1 diabetes and HbA1c below 7·5% is safe and well tolerated, improves glucose control, and reduces hypoglycaemia burden." (PMID 28094136, 2017). "The aim of this study was to evaluate the effects of antioxidants lycopene and insulin on histological changes and expression of Bcl-2 family genes in the hippocampus of streptozotocin-induced type 1 diabetic rats." (PMID 28656152, 2017). "The discovery of insulin in 1921 represented a decisive breakthrough in the prognosis of type 1 diabetes, which had previously been a fatal disease." (PMID 28620331, 2017). "The diagnosis of type 1 diabetes is often followed by a partial clinical remission phase which is marked by the recovery of surviving beta cells and increased endogenous insulin production." (PMID 28459844, 2017).
type 1 diabetes (continued). "In contrast, a crossover randomized study in type 1 diabetes, comparing insulin glargine to insulin detemir showed similar blood glucose control, however there was an increase in the number of daily injections and higher doses with detemir." (PMID 28970434, 2017). "For the mapping of the selected disease to ATC, levothyroxine was used as marker for dysthyroidism, and insulin as a marker for type I diabetes." (PMID 28962565, 2017). "Type 1 diabetes (T1D) is an autoimmune disease in which immune-mediated targeting and destruction of insulin-producing pancreatic islet β cells leads to chronic hyperglycemia." (PMID 29033899, 2017). "Episodic hypoglycemia is an almost inevitable consequence of exogenous insulin treatment of type 1 diabetes, and in up to 30% of patients, this can lead to impaired awareness of hypoglycemia." (PMID 28293906, 2017). "At the clinical onset of type 1 diabetes, remaining beta cells produce insufficient insulin to prevent persistent hyperglycaemia, with its classic symptoms of polyuria, polydipsia and polyphagia." (PMID 28550517, 2017). "Subsequently, he was discharged home on an insulin regimen for presumed new onset insulin dependent diabetes mellitus (IDDM) and prednisone taper for colitis." (PMID 29254501, 2017). "Type 1 diabetes is a chronic autoimmune disease characterized by immune-mediated destruction of the pancreatic insulin-producing beta cells by autoreactive CD4+ and CD8+ T cells." (PMID 29387056, 2017). "As in other studies of type 1 diabetes and metformin, HbA1c was only transiently improved by metformin and reverted to baseline over the first 6 months of use, probably as insulin doses were down-titrated by patients in an effort to avoid hypoglycaemia." (PMID 28770327, 2017). "Detectable UCPCR in pregnant women with normal glucose tolerance and type 1 diabetes is likely to reflect endogenous insulin secretion and hence β-cell activity." (PMID 28090333, 2017). "Social media such as Facebook as a tool can assist in standard medical care to improve glucose control in a long term period in adolescents with type 1 diabetes using insulin pump therapy." (PMID 30291064, 2017). "Type 1 diabetes is a T cell-mediated autoimmune disease, whereas T2D is the result of peripheral cell resistance to endogenous insulin." (PMID 29259578, 2017). "A possible link between type 1 diabetes and 25(OH)D has been suggested to be via its inverse correlation with HbA1c and its positive correlation with insulin, which is mediated by body fat." (PMID 29273017, 2017). "Results from our study, together with those from previous studies in different target groups, support the benefits of closed-loop insulin delivery in a broad population with type 1 diabetes." (PMID 28094136, 2017). "The ViDa1 questionnaire discriminated between variables that are relevant in the treatment of patients with type 1 diabetes: glycemic control, carbohydrate count, type of insulin treatment, and presence of chronic complications." (PMID 28620331, 2017). "Type 1 diabetes is a debilitating disorder which requires life-long exogenous insulin administration." (PMID 29017529, 2017). "In pregnancy, urinary C peptide creatinine ratio (UCPCR) reflects endogenous insulin secretion in women with normal glucose tolerance and type 1 diabetes." (PMID 28090333, 2017). "To determine the extent to which beneficial effects of PF are attributable to insulin sensitivity, we utilized a type 1 diabetes model." (PMID 29221204, 2017). "It should be noted that these studies were conducted before the routine use of insulin for intensive treatment of type 1 diabetes." (PMID 28291006, 2017). "As a result, we now know that type 1 diabetes is an autoimmune disease arising from the destruction of pancreatic insulin-producing beta cells." (PMID 28770323, 2017). "Type 1 diabetes is an autoimmune disease that affects pancreatic β cells producing insulin, resulting in the dysregulation of glucose metabolism." (PMID 29088299, 2017).